MMP3 (matrix metallopeptidase 3)
Diseases named in the same sentence as MMP3 in open-access papers (continued):
Sharing a sentence is not in itself a finding about the gene and the disease.
rheumatoid arthritis (continued). "In the rheumatoid arthritis pathway, TGF-β1 induced Ccl2 and suppressed Ctsl and Mmp3." (PMID 33149203, 2020). "The MMP-3 in the SF samples of dogs with rheumatoid arthritis is elevated but gene expression of MMP-3 was not different in a canine CrCLR model compared to normal dogs." (PMID 33211763, 2020). "Also, RF positivity, SJC-28, TJC-28, CRP, erythrocyte sedimentation rate (ESR), uncarboxylated osteocalcin (ucOC), MMP-3, TNF-α, IL-6, disease Activity Score-28 for Rheumatoid Arthritis with ESR (DAS28-ESR) levels were alleviated." (PMID 31013659, 2019). "Furthermore, several genes that were annotated in studies on rheumatoid arthritis (VEGFA, TGFB2, MMP1, MMP3, IL8, CCL3L1, CTSL1, CCL2) were also significantly upregulated in the immature articular cartilage in our study." (PMID 27045355, 2016). "This may explain why, while MMP-3 levels in SF of rheumatoid arthritis (RA) patients are extremely high, depletion of MMP-3 in animal models does not prevent cleavage of aggrecan, nor does it prevent or reduce cartilage destruction observed in specific forms of arthritis." (PMID 16859524, 2006). "Hegemann and colleagues demonstrated in canine rheumatoid arthritis that the amount of TIMP-1 was not sufficient to block the increased MMP-3 activity." (PMID 15642138, 2005). "Andrographolide reduces MMP-1, MMP-3, and MMP-9 expression of rheumatoid arthritis fibroblast-like synoviocytes (RA-FLS) in hypoxia, decreasing HIF-1α expression and interfering with HIF-1α binding to DNA." (PMID 33374961, 2020). "In fact, serum MMP-3 levels are related to inflammation and tissue damage in conditions such as rheumatoid arthritis, where synovial macrophages are crucial in early MMP activity and serum MMP-3 may be a biomarker of disease activity and predictor of joint destruction." (PMID 29599896, 2018). "Rheumatoid Arthritis (RA): Especially in non-acute phases, H2S inhibits fibroblast-like synoviocyte proliferation, reduces IL-6 and MMP-3 production, and blocks NF-κB activation, thereby reducing joint destruction." (PMID 41226825, 2025). "Rheumatoid arthritis (RA) is characterized by increases in MMP-2, MMP-3, and MMP-9." (PMID 36830637, 2023). "Gastrodia elata Blume (GE) is a traditional Chinese herbal medicine with anti-inflammatory activity, and according to a study, GE significantly decreased the IL-6, CXCL8, MMP-3 and MMP-13 levels in TNF-induced rheumatoid arthritis fibroblast-like synoviocytes (RA-FLSs)." (PMID 36439173, 2022). "The production of chemokines (such as MCP-1, IL-8) is also increased in endothelial cells, rheumatoid arthritis fibroblast-like synoviocytes (RA-FLS) and mononuclear cells, as is the synthesis of RANK-L by RA-FLS, and that of MMP-1, MMP-3 and MMP-13 in chondrocytes." (PMID 25604317, 2015). "IgM, IgG, CH50, and MMP‐3 are within the normal range, and the elevated CRP and ESR are considered to be due to the ulcer rather than the activity of rheumatoid arthritis." (PMID 40321227, 2025). "Cipemastat, which inhibits MMP-1, MMP-3, and MMP-9, was used for the treatment of rheumatoid arthritis and osteoarthritis, but it was not shown to prevent the progression of joint damage in patients." (PMID 33419373, 2020).
Arthritis (125 papers, 2005 to 2026). Inflammation of a joint. "MMP-9 promotes the migration and invasion of FLS in collagen-induced arthritis in mice, whereas MMP-3 causes FLS to migrate to adjacent cartilage and induces articular cartilage degradation." (PMID 32568738, 2020). "We found that inhibition of IL-17 during established arthritis caused only a modest decrease in the local expression of MMP3, MMP13 and IL-23, but a marked reduction in systemic IL-6 levels, in accordance with previous reports." (PMID 26081345, 2015). "The role of Mmp-3 was analyzed in antigen-induced arthritis and collagen-induced arthritis models, and a similar incidence and severity of arthritis was displayed by Mmp3-deficient and control mice in both arthritis models." (PMID 21190566, 2010). "Notably, some dermal DEGs (Tnfsf11, Ctsk, Mmp3, Mmp8, etc.)were associated with osteoclast differentiation and activation, which is linked to arthritis." (PMID 40471688, 2025). "These potentially include NO production via rhythms in Nos2 expression and rhythmic MMP3 production, both previously linked to arthritis-associated joint damage and regulation of inflammation, as well as other inflammation-associated disease effectors (Cxcl5, Ccl20, Mmp13, Rankl/Tnfsf11)." (PMID 38981514, 2024). "Moreover, our preliminary study verified the cytokines (TNF-α, IL-1β) and inflammatory mediators (MMP-1, MMP-3) associated with joint inflammation in animal models." (PMID 34190191, 2021). "MMP3 has also been associated with pathological processes, such as tumor metastasis and arthritis." (PMID 22897899, 2012). "Gain or loss of function from individual arthritis-related miRNAs such as miR-155 could also lead to similar expression regulation of proinflammatory proteins including MMP3 and MMP13, which suggested that partial function of DICER1 could be achieved through its downstream miRNAs." (PMID 31275058, 2019). "All of these beneficial impacts of DAPA were reflected in the improvement of AI, gait score, and paw swelling, along with the reduced levels of RF, MMP-1, and MMP-3 arthritis markers." (PMID 40350466, 2025). "PCB group showed significantly lower body weight (p = 0.0075), higher arthritis score (p < 0.0001) higher width of paws (p < 0.0001) and higher serum MMP-3 (p < 0.0001) compared to CO group, indicating that the CIA model was induced successfully." (PMID 41230096, 2025). "To determine the specific activity of key MMPs implicated in arthritis, we performed ELISAs for MMP1, MMP3, and MMP13." (PMID 40491903, 2025). "MMP-3 has been identified as a potential therapeutic target in various inflammatory diseases, including joint inflammation and OA, as well as obesity, pulmonary inflammation and periodontitis." (PMID 41020853, 2025). "Multiple drugs (e.g., CKD-506, T-5224, Roflumilast) are under investigation to disrupt this specific interaction of AP-1 at the MMP3 promoter, and AP-1 signaling targets more broadly, in models of arthritis as well as clinical trials of RA patients." (PMID 38821936, 2024). "The serum MMP-3 concentration during the active phase of arthritis was > 15.0 ng/mL in all patients." (PMID 37336934, 2023). "The median serum concentration of MMP-3 at arthritis diagnosis and during arthritis remission was 93.7 ng/mL (IQR, 68.9–132.3 ng/mL) and 20.3 ng/mL (IQR, 15.0–28.2 ng/mL, p < 0.001), respectively." (PMID 37336934, 2023). "Serum and synovial fluid MMP-3 levels were increased in patients with arthritis compared to controls." (PMID 37482815, 2023). "The content of MMP-3 was increased in the mouse arthritis model and the administration of baicalin can reduce the gene expression level of MMPs and alleviate inflammatory processes." (PMID 34940198, 2021). "In CIA animal models, intra-articular adiponectin administration attenuates arthritis by downregulating IL-1, MMP-3, and TNF-α expression in inflamed joints." (PMID 34685605, 2021).
Arthritis (continued). "We stimulated TNFα-pretreated OA- and RA-SF with 10–11 to 10–14 M PK2 and measured the cell culture medium concentration of the arthritis-aggravating factors IL-6 and MMP-3 and arthritis-inhibiting factors TIMP-1 and OPG." (PMID 34526577, 2021). "Another study showed that GDF11 inhibited the expression of MMP‐3 in the collagen‐induced arthritis." (PMID 33764670, 2021). "Administration of T-5224 prevents arthritis in a mouse model by reducing the amount of MMP-3 in vivo in sera and joints and in vitro in synovial cell and chondrocyte cultures." (PMID 33573315, 2021). "MMP3 breaks down extracellular matrix proteins in normal physiological processes as well as disease processes such as arthritis and tumor proliferation." (PMID 31052496, 2019). "This study showed that the combined treatment with etanercept and tacrolimus reduced the number of peripheral CD11bhigh OCPs and serum MMP-3 levels and attenuated the progression of arthritis in hTNF-Tg mice." (PMID 31949424, 2019). "MMP-3 and M-CSF appear to be biomarkers of arthritis, differentiating patients with PsA from those with PsC, and patients with SpA from HC." (PMID 28934972, 2017). "One noteworthy finding was that the knee joints of V-KO mice had nearly 4-fold less MMP-3 gene expression compared to their WT counterparts on day 13 of arthritis, consistent with the reduced cartilage and bone erosion scores." (PMID 29216931, 2017). "In general, our results highlight the marathon related increase in MMP-3 and YKL-40 which are recognized biomarkers of cartilage degradation associated with arthritis." (PMID 25333960, 2014). "In arthritis research, increased levels of MMP-3, YKL-40 and COMP in the circulation are recognized as biomarkers of cartilage turnover and/or destruction." (PMID 25333960, 2014). "IFN-γ also inhibits IL-1b-mediated production of MMP-1 and MMP-3 by synovial fibroblast in the early phase of arthritis." (PMID 23613752, 2013). "This study demonstrated that early intervention of HA is an effective protection against accumulation of inflammation-induced HIF-1alpha, iNOS, and MMP3 to limit erosive damage in CFA-induced model of arthritis." (PMID 21679445, 2011). "These validation analyses provides compelling evidence that the proposed read-out parameters, MMP-3, anti-collagen IgG2a, and Larsen and micro-CT calcaneus score, are most applicable to detect changes in different aspects of arthritis severity upon treatment." (PMID 20731827, 2010). "Recent studies identified MMP-3 as a target for T-cell recognition in both experimental arthritis and RA but also in age-matched healthy adult controls." (PMID 17129378, 2006). "IL-4 overexpression in the arthritic knee joint strongly and locally inhibited the mRNA expression of MMP-3 in mice with collagen-induced arthritis." (PMID 15642138, 2005). "IFN-γ-stimulated arthritis induced a marked increase in MMP-3, MMP-12 and MMP-13 mRNA levels in the cartilage layers of both WT controls and p47phox-/- mice, in comparison with the cartilage of naive knee joints (Δ Ct ranging from 3 to 9)." (PMID 15987491, 2005). "The role of cathepsin B, for instance in activation of pro-MMP-3 and its regulation in arthritis, was recently reviewed by Yan and Sloane." (PMID 15642138, 2005). "MMP3 is a member of the matrix metalloproteinase family, which can digest matrix proteins and other extracellular matrix components, and is positively correlated with arthritis." (PMID 40455747, 2025). "Notably, serum MMP-3 was significantly elevated during the acute phase of arthritis in all patients." (PMID 37336934, 2023). "MMP3 is involved in the breakdown of extracellular matrix in arthritis and metastasis." (PMID 36105284, 2022).
Arthritis (continued). "Among the five variables, including age, serum levels of ferritin, IL-18, and MMP-3 level, and days of illness at the onset of arthritis, only ferritin showed a significant difference among interval fever-onset, continued fever-onset/non-biologic, and continued fever-onset/biologic patients." (PMID 34354966, 2021). "Four proteases associated with arthritis, neutrophil-derived human elastase (HNE) and Cathepsin G (CG), fibroblast-derived matrix metalloproteinase 3 (MMP-3) and the serine protease dipeptidyl peptidase-IV (DPP-IV), were investigated for their ability to process HMGB1." (PMID 33391251, 2020). "Similarly, MMP-2- and MMP-3-knockout mice are manifested with more severe arthritis than the wild-type mice." (PMID 32518385, 2020). "Similarly, MMP-3 contributes to tissue damage in neutrophil-mediated pathologies, including arthritis and acute pulmonary inflammation." (PMID 32645949, 2020). "Matrix metalloproteinase-3 (MMP-3) participates in normal extracellular matrix turnover during embryonic development, organ morphogenesis and wound healing, and in tissue-destruction associated with aneurysm, cancer, arthritis and heart failure." (PMID 31827179, 2019). "MMP-3 and M-CSF are biomarkers for the presence of arthritis in psoriatic disease, and could therefore be used to screen for PsA in psoriasis cohorts." (PMID 28934972, 2017). "Moreover, Cd addition correlated with a reduced MMP-3/TIMP ratio, previously associated with low destruction and a reduced inflammation, in line with the observations made in the in vivo model of arthritis after intra-articular Cd injections." (PMID 28742830, 2017). "Arthritis incidence, severity of joint inflammation, pannus formation, skeletal damage, hematogenous dissemination of the infection, matrix metalloproteinase 3 (MMP3) levels, and interleukin-17 expression levels were evaluated." (PMID 27405639, 2016). "Although serum MMP-3 levels alone are a crude reflection of disease progression, they presumably reflect the levels of other joint-destroying MMPs as well, as for example shown in the collagen-induced arthritis model in mice." (PMID 26922083, 2016). "Interestingly, the ACG/Jacalin index had a higher correlation coefficient for joint parameters than CRP or MMP-3, suggesting that this index is a more specific arthritis marker." (PMID 27209430, 2016). "Moreover, gene expression of Mmp-3 was upregulated in the cartilage of FrzB−/− mice with mBSA-induced arthritis compared with wild-type mice." (PMID 24984954, 2014). "The therapeutic influence of OPG may be attributed to blockage of osteoclastogenesis and negative regulation of other arthritis-associated mediators such as IFN-γ and MMP3." (PMID 24222748, 2013). "Although OPG therapy alone appears to be not very effective in controlling the inflammatory natures of the disease such as synovitis and pannus formation, modification of OPG expression in the arthritis joint resulted in diminished gene expression of MMP3 and INF-γ." (PMID 24222748, 2013). "However, after induction of arthritis, we observed the local up-regulation of pro-inflammatory IL-6 and MMP-3 in both HO-1+/− and HO-1−/− animals with respect to wild type mice." (PMID 23285041, 2012). "This study demonstrated that early intervention of HA is an effective protection against accumulation of inflammation-induced HIF-1α, iNOS, and MMP3 and might limit the erosive joint damage of arthritis." (PMID 21679445, 2011). "Matrix metallopeptidase 3 (MMP3) may affect the extracellular milieu of adipose tissue akin to that in arthritis." (PMID 17183659, 2006). "Furthermore, the presence of joint inflammation on WBMRI and clinical examination was associated with higher serum concentrations of MMP-3 and VEGF, respectively, supporting a relation between imaging findings and the pathophysiological processes involved in JIA." (PMID 38244609, 2024).
Arthritis (continued). "Thus, the treatment of JWH133 could suppress other inflammatory mediators than IL-6, CCL2 and MMP-3, which are involved in pathology of the arthritis." (PMID 25115332, 2014). "The dynamic balance between MMP-3 and TIMP-1 determines the direction of cartilage metabolism, and monitoring their levels helps assess arthritis severity and treatment efficacy." (PMID 41458513, 2025). "MOIG treatment inhibited the production of IL-1β, IL-6, IL-8 and TNF-α, and reduced the matrix degradation enzymes expressions of MMP2 and MMP3 in TNF-α-stimulated FLSs, thereby blocking the spread of arthritis to distant joints." (PMID 39444614, 2024). "MMP3 and MMP13 are arthritis-related genes, while Cdkn genes that negatively regulate cell proliferation and are often considered to be related to cell senescence." (PMID 39220112, 2024). "Interleukin-10 (IL-10), IL-1β, mitogen-activated protein kinase (MAPK), IL-6, matrix metalloproteinase-3 (MMP-3), TNF-α and other targets have been confirmed to play important roles in the treatment of arthritis by CC." (PMID 37637408, 2023). "MMPs such as MMP2, MMP3, and MMP9 are up-regulated in arthritis, leading to damage to bones and cartilage of joints via activation of IL1β, TNFα, and many other cytokines." (PMID 37765197, 2023). "At the molecular level, CC plays a critical role in the treatment of arthritis by regulating NF-κB, Wnt1/β-catenin and PI3K/AKT/mTOR signaling pathway, inhibiting the expression of IL-6, IL-1β, MMP-3 and TNF-α." (PMID 37637408, 2023). "According to our findings, rats with MIA-induced arthritis had marked elevation in serum levels of ADAMTS-5 and MMP-3 than did normal rats." (PMID 37259405, 2023). "For arthritis, iguratimod has been demonstrated to inhibit serum MMP-1 and MMP-3 of RA patients; while in bleomycin-induced interstitial lung disease, iguratimod increased the level of MMP-9 of lung tissues." (PMID 37596660, 2023). "In the present study, we observed chondroprotective effects in an animal model of arthritis and selective suppression of MMP-1/MMP-3 in RASFs using a CDK4/6 inhibitor." (PMID 34849618, 2022). "TGP can also inhibit joint destruction in rats with collagen-induced arthritis by decreasing the secretion or production of vascular endothelial growth factor (VEGF), basic fibroblast growth factor (bFGF), MMP-1, and MMP-3 from fibroblast-like synoviocytes." (PMID 35186100, 2022). "Clinical data have shown that MMP3 and MMP13 are highly expressed in the cartilage of patients with arthritis, resulting in OA progression." (PMID 33809253, 2021). "Interstitial collagenase (MMP-1), stromelysin-1 (MMP-3), and collagenase 3 (MMP-13) appear to degrade the components of the cartilage ECM in arthritis." (PMID 32937098, 2021). "After 10 weeks of loganin treatment, arthritis was evaluated histologically by safranin O staining; immunohistochemistry of COX-2, MMP-3, and MMP-13; and micro-computed tomography (micro-CT)." (PMID 33567513, 2021). "In vivo, the inhibition of TRAF6 using mice-specific TRAF6 siRNA inhibit serum anti-collagen II antibodies, MMP-1, MMP-3, and MMP-9, thereby reducing the severity of arthritis and joint inflammation." (PMID 33294443, 2020). "Interestingly, despite the convincing human data, the role of MMP-3 could not be confirmed in animal models, since disease severity was not altered in MMP-3-deficient mice in two antigen-induced arthritis models." (PMID 30949048, 2019). "Our results suggest that T-614 yields a strong improvement in arthritis via exact suppression of RANKL/OPG, IL-17, and MMP-3 expression in RASFs." (PMID 26273599, 2015). "The present study has been designed to use the adjuvant-induced arthritis model to examine the effects of HA on the changes of immunohistochemical expressions of HIF-1α, iNOS, and MMP3 in the synovial tissues in the early phase of arthritic inflammation." (PMID 21679445, 2011).